TNF (tumor necrosis factor)
Diseases named in the same sentence as TNF in open-access papers (continued):
Sharing a sentence is not in itself a finding about the gene and the disease.
acute lung injury (continued). "NF-κB activation is a critical transcription factor required for the maximal expression of many inflammatory cytokines and chemokines (e.g., TNF-α, IL-1β, IL-6, and MIP-2) involved in the pathogenesis of acute lung injury." (PMID 23710113, 2013). "We examined the antioxidant and anti‐inflammatory effects of the methanolic extract of Dendranthema oreastrum (Hance) Y.Ling, commonly known as “Gu‐Jeol‐Cho” in Korea and widely found across East Asia, using an LPS‐induced acute lung injury (ALI) mouse model and TNF‐α‐stimulated NCI‐H292 cells." (PMID 40265676, 2025). "An increasing number of studies have shown that in animal models of ischemia-reperfusion (I/R) and acute lung injury (ALI), NGR1 attenuates the expression levels of the inflammatory factors IL-6, TNF-α, and IL-1β and attenuates injury, leading to interventional protection against the disease." (PMID 38109303, 2023). "TNF-α is a key regulatory molecule in the development of both direct (e.g., pneumonia) and indirect (e.g., non-pulmonary sepsis) phenotypes of acute lung injury (ALI)." (PMID 36835507, 2023). "In addition, in a mouse model induced by LPS, we determined that sino reduced the lung index and the levels of myeloperoxidase (MPO), NO, IL-6 and TNF-α in lung tissues and bronchoalveolar lavage fluid (BALF) in acute lung injury (ALI)." (PMID 34801005, 2021). "Increased miR-150 decreases neutrophil counts and production of inflammatory cytokines IL-1β, IL-6, and TNF-α along with levels of total protein, albumin and IgM in the BAL fluid in LPS-induced acute lung injury mice in vivo, as well as alleviating LPS-induced A549 cell apoptosis in vitro." (PMID 32315984, 2020). "The acute lung injury (ALI) mouse model was successfully induced by smoke inhalation, as confirmed by the aberrantly modified cell numbers of red blood cells and neutrophils counts, increased levels of TNF-α, IL-1β, Bax, caspase-7, caspase-3, and decreased Bcl-2 content in lung tissues." (PMID 35152840, 2022). "In a lipopolysaccharide-induced acute lung injury (ALI) rat model, the injection of Ang-1 modified human umbilical cord derived MSCs (hUC-MSCs) could decrease the expression of pro-inflammatory cytokines (e.g., TNF-α, TGF-β1) and increase the expression of anti-inflammatory cytokine IL-10." (PMID 37055866, 2023). "Therefore, the covalent HC-HA binding, which is exclusively mediated by tumor necrosis factor α (TNFα)-stimulated-gene-6 (TSG-6), may play an important role in the onset or the resolution of lung inflammation in acute lung injury (ALI) induced by respiratory infection." (PMID 29855321, 2018).
liver failure (94 papers, 2005 to 2026). A liver disease characterized by the liver losing or has lost all of its function. "Since TNF-α is associated with diastolic dysfunction, it is likely to affect the progress of myocardial injury in patients with advanced liver failure." (PMID 26665009, 2015). "α-Amanitin has been shown to act synergistically with cytokines such as tumor necrosis factor-alpha (TNF-α) and this may be the final cause of liver failure." (PMID 39165585, 2024). "The synergistic action of endogenous cytokines such as TNF-α with α-amanitin-sensitized cells may be the final cause of liver failure." (PMID 39165585, 2024). "The final cause of liver failure may be the synergistic effect of endogenous cytokines such as TNF-α with xenobiotic-sensitized cells." (PMID 39165585, 2024). "Increased level of TNF-α is associated with hepatic inflammation, necrosis and hepatic failure." (PMID 35594248, 2022). "Moreover, Dejager and Libert showed that TLR-9 signals caused hepatocyte exhaustion and hepatic failure by promoting TNF-α production." (PMID 25892855, 2015). "Liver failure often occurs seven days after an insult, thus an association between the detected peak in liver TNF-α expression and liver failure may be present." (PMID 19594900, 2009). "Moreover, experimental models have shown that zinc-deficient mice with hepatic failure exhibit greater neuroinflammation, upregulation of proinflammatory cytokines (e.g., TNF-α, IL-6), and worse performance in spatial memory tests compared with zinc-replete controls." (PMID 40362419, 2025). "Furthermore, TNF-a may cause hepatic cellular damage by increasing glomerular mononuclear cell infiltration, hence hastening the course of liver failure." (PMID 36466832, 2022). "During liver failure, aptamer targets TNF and CRP mainly by inhibiting TNF and tracking the site of CRP secretion, thereby blocking the inflammatory process and reducing and eliminating inflammation." (PMID 38305844, 2024). "Inflammatory stress and cell damaging agents which are released by macrophages (ROS, TNFα) are known to throttle the network of LETFs and drive liver failure." (PMID 38755249, 2024). "TNF-α administration has been improved to accelerate hepatic failure, while TNF-α production inhibition or TNF-α knockout efficiently prevents acute liver injury." (PMID 36904149, 2023). "The EZH2 inhibitor GSK126 has been shown to ameliorate liver injury and improve survival in mice with liver failure by inhibiting TNF and other indispensable pro-inflammatory cytokines." (PMID 37781509, 2023). "In a mouse model of hepatic failure induced by the intraperitoneal administration of tumor necrosis factor alpha (TNF-α) and D-galactosamine, the administration of BM-MSC-derived EVs resulted in the infiltration of protective immune cells into the liver." (PMID 37893181, 2023). "A study has shown that systemic EZH2-catalyzed H3K27me3 expression increases during liver failure, while its enrichment on the TNFα promoter in Kupffer cells decreases." (PMID 37781509, 2023). "Our experiment found that the reduction of serum IL-2 levels in patients with advanced PBC liver failure will lead to a decrease in Th1 type cells (serum TNF-α level in the blood approaches the normal value)." (PMID 36159788, 2022). "Recently, it was discovered that in Acetaminophen (APAP)-induced liver failure, Tumor Necrosis Factor Alpha (TNF-α)/LipoPolySaccharide (LPS) MDSCs served a protective role by reducing intrahepatic infiltration of activated neutrophils." (PMID 34869447, 2021). "We demonstrated the protective role of MDSCs and therapeutic effect of TNF-α/LPS MDSCs in APAP-induced liver failure." (PMID 33250891, 2020). "Because TNF is known to play a role in renal and hepatic failure, kidneys and livers were also examined for organ injury." (PMID 32410851, 2020). "The TNF‐α/HMGB1 inflammation signalling pathway plays an important role in pyroptosis during liver failure and AKI." (PMID 32419317, 2020).
liver failure (continued). "The results suggested that EZH2/H3K27me3 promoted the progression of liver failure and that TNF, along with downstream NF-κB and Akt signaling pathways, was manipulated by epigenetic modification with H3K27me3." (PMID 33262329, 2020). "Previous studies have persistently reported the activation of microglia cells, increased inflammatory factor levels (e.g., TNF, IL-6, and IL-1β), Alzheimer's type II astrocytosis, and neuronal cell death in patients with liver failure." (PMID 32256557, 2020). "Tumor necrosis factor (TNF) induced apoptosis plays an important role in the development of liver failure." (PMID 31317042, 2019). "In lethal hepatic failure induced in mice by D-gal/TNF-α, systemic intraperitoneal or intravenous administration of either human or murine MSC-EV decreased hepatic necrosis and increased survival." (PMID 31270691, 2019). "Serum TNF was increased substantially in liver failure mice with the vehicle (DMSO) treatment, peaked at 1 h, and gradually decreased till 4 h." (PMID 29789597, 2018). "TNF-α and IL-1β, the two major pro-inflammatory cytokines, stimulated the matrix metalloproteinases, and ultimately resulted in liver failure." (PMID 29723988, 2018). "Our data suggest that there was a correlation between increased EZH2/H3K27me3 and upregulated TNF in liver failure." (PMID 29789597, 2018). "Clinical trials and animal experiments have showed that liver failure also significantly increased some inflammatory molecules including cytokines interleukin-1 (IL-1), interleukin-6 (IL-6), and tumor necrosis factor-alpha (TNF-α) in plasma." (PMID 30041501, 2018). "In conclusion, EZH2 and H3K27me3 contributed to the pathogenesis of liver failure via triggering TNF and other indispensable proinflammatory cytokines." (PMID 29789597, 2018). "Because 60% (39/65) of mice with LPS/D-GalN-induced ALF died within 12 h and displayed serum biochemical markers and liver morphology consistent with liver failure, we chose a 12-h time point to assess the effect of anti-TNF-α IgG antibodies on liver failure." (PMID 30134917, 2018). "Therapeutic effects of bone‐marrow derived mesenchymal stem cells (MSC) and vesicles released by these cells were examined in a lethal murine model of hepatic failure induced by d‐galactosamine/tumor necrosis factor‐α (TNF‐α)." (PMID 28213967, 2017). "The coadministration of TNF‐α and d‐galactosamine results in hepatic failure, characterized by tremulousness, an impaired ability to walk straight or to recover from a supine position, loss of eyelash reflex and eventual coma." (PMID 28213967, 2017). "Transgenic mouse models expressing high levels of cytokines typically found in human AIH, such as interferon-γ (IFN-γ) and tumor necrosis factor-α (TNF-α), induced acute liver inflammation, hepatocyte apoptosis and hepatic failure." (PMID 25603179, 2015). "In conclusion, TNF-α antagonist-related liver injury is an underrecognized, important clinical entity with potentially serious consequences, such as liver failure." (PMID 24707412, 2014). "Hepatic failure and tissue destruction as a result of endogenously produced TNF are mediated by the 55-kDa TNFR1." (PMID 24303082, 2013). "Despite the failure of antibodies directed to TNF/TNFRp55, effective blocking of this pathway remains a target for the reduction of hepatocyte damage and subsequent liver failure." (PMID 23874752, 2013). "The present study suggests that the LPS-macrophage activation-TNF-α-axis is the core of secondary liver injury leading to liver failure." (PMID 21747711, 2011). "On the other hand, excessive TNF-α production between 12 and 24 hours after liver resection was considered to be a major determinant of liver failure." (PMID 19079544, 2008). "Analyses of serum revealed elevation of proinflammatory cytokines (TNF alpha, IL-6), cytokines (IL-2R), anti-inflammatory cytokines (IL-4) and chemokines (IL-8) as well as signs of rhabdomyolysis and hepatic failure." (PMID 16285034, 2005).
liver failure (continued). "TNF-α promotes programmed cell death of intestinal epithelial cells by activating caspase-3, which primarily contributes to increased permeability of the intestinal barrier in animals experiencing severe liver failure." (PMID 39479215, 2024). "Studies have documented, in HE patients and rodent models with liver failure, the activation of microglia and hepatic macrophage, together with increases in pro-inflammatory factors, including tumor necrosis factor alpha (TNF-α), interleukin-1 beta (IL-1β), and interleukin-6 (IL-6)." (PMID 38725082, 2024). "Treatment with L. sativum and tadalafil, either alone or in combination, resulted in a significant (p < 0.0001) decrease in IL-1β and TNF-α levels in the liver tissue when compared to the CCL4-induced liver failure group, with a possibly superior effect for the tadalafil-L." (PMID 38413963, 2024). "On the one hand, TNF-α mediates hepatocyte apoptosis and liver failure in diverse toxicity models." (PMID 36831304, 2023). "In addition, the particle also exerts anti-oxidant and anti-apoptotic properties, thereby attenuating liver failure and improving survival rate in mice challenged by D-galactosamine plus TNFα." (PMID 37398640, 2023). "The LPS/Dgal-liver-failure mouse model is well known to be dependent on TNFα." (PMID 36423130, 2022). "To test this hypothesis, we investigated the effect of C14-Tri-LAN-Gly on TNF-α/D-GalN-induced liver failure." (PMID 33746949, 2021). "Previous studies reported that LPS/D-GalN induced secretion of inflammatory cytokines, such as tumor necrosis factor (TNF)-α, interleukin (IL)-6, and IL-1β in mice model of hepatic liver injury, which promote liver cell necrosis, hepatic failure and reduce antioxidant enzyme activity." (PMID 34573019, 2021). "The hepatic levels of IL-6 and TNF-α in the HFD group were significantly elevated by 49.4% (p < 0.05) and 69.1% (p < 0.05), respectively, compared to those in the ND group, indicating that HFD caused a typical liver failure inflammatory response." (PMID 34829565, 2021). "TNF-α acts as a pleiotropic molecule, because in the absence of Akt and NF-κB activation signaling, TNF-α mediates hepatocyte apoptosis and liver failure in mice." (PMID 31952110, 2020). "Previous models of TSS in HLA-DR1 mice required d-galactosamine pretreatment to elicit liver failure, an event that is entirely related to tumor necrosis factor (TNF)-induced hepatocyte apoptosis in the d-galactosamine setting, while SEB alone results in cytokine release only." (PMID 31597722, 2019). "In lethal hepatic failure induced by D-galactosamine (D-gal)/TNF-α in mice, administration of MSC-EV increased the number of F4/80+ macrophages in the liver concomitant with a reduction in the levels of circulating pro-inflammatory cytokines and attenuation of liver inflammation." (PMID 31270691, 2019). "LPS and/or TNF-α is involved in the vicious circle to destroy the hepatocytes, which may result in liver failure." (PMID 31183000, 2019). "Notably, using GSK126 inhibiting EZH2/H3K27me3 directly in vitro significantly reduced TNF in the current study, which raises an interesting question: how do EZH2 and H3K27me3 modulate the proinflammatory cytokines, especially TNF during liver failure." (PMID 29789597, 2018). "GSK126 ameliorated disease severity in liver failure mice, which maybe attribute to down-regulate circulating and hepatic proinflammatory cytokines, especially TNF via reducing H3K27me3." (PMID 29789597, 2018). "Furthermore, inhibitor GSK126 for EZH2-catalysed H3K27me3 ameliorated liver injury and improved survival in liver failure mice, via suppressing TNF and other indispensable proinflammatory cytokines." (PMID 29789597, 2018). "Compared to directly binding on Tnf promotor as a transcription factor, EZH2 regulated TNF in liver failure might be largely due to its methylation activity and its downstream product (H3K27me3)." (PMID 29789597, 2018).
liver failure (continued). "We found higher levels of TNFα within the portal blood, which could support the role of the portal blood microbiota in inducing a “cytokine storm”, exacerbating liver failure and clinical symptoms." (PMID 29844325, 2018). "However, GSK126 inhibited serum TNF substantially (P < 0.05), compared to that from the vehicle-treated liver failure mice." (PMID 29789597, 2018). "We examined hepatic histomorphology and circulating biochemical markers of hepatic injury 6 hours after i.p. administration of MSC‐EV or PBS (controls) to examine their impact on hepatic injury induced by d‐galactosamine/TNF‐α prior to hepatic failure and death." (PMID 28213967, 2017). "Acteoside could effectively inhibit TNF-α-mediated hepatic apoptosis and the subsequent necrosis in DGalN/LPS-induced liver failure." (PMID 29344414, 2017). "The body produces endotoxins to activate TNFα release during liver failure." (PMID 29156683, 2017). "D-Galactosamine (GalN)/lipopolysaccharide (LPS)-induced liver failure in mice is dependent on macrophage-derived pro-inflammatory cytokines, including tumor necrosis factor (TNF)-α, interleukin (IL)-1β, IL-6 and interferon-γ, and accurately represents human FHF." (PMID 25623171, 2015). "It has been demonstrated that TNF plays an important role in the pathogenesis of liver failure." (PMID 23874752, 2013). "However, these mice succumbed of liver failure by a TNFα-signaling-dependent cell death demonstrating also the importance of TIMP-3 in controlling TNFα bioavailability." (PMID 23091735, 2012). "On one hand, TNF mediates hepatocyte apoptosis and liver failure in mice in a number of toxicity models; many of these studies also demonstrate a protective effect of NF-κB activation against the cytotoxic effects of TNF." (PMID 24710554, 2012). "In summary, low serum AHSG level and intestinal endotoxemia are critical pathological states in subjects of liver failure, while the peripheral blood mononuclear cells and inflammatory factors such as TNF-α and IL-6 are important immune targets in the pathological process of liver failure." (PMID 21747711, 2011). "In addition, following partial hepatectomy these mice succumbed to liver failure, indicating the importance of TNF signaling in liver regeneration." (PMID 21980496, 2011). "Second, substantial amounts of AHSG may be consumed in the inhibition of increased expression of cytokines (such as TNF-α) during liver failure." (PMID 21747711, 2011). "Moreover, we have suggested the activation of related signaling transduction could induce Bcl-2 expression and inhibit Bad, TNF-α and IL-1β expression, which could ameliorate the apoptosis and necrosis of hepatocytes to prevent the liver failure." (PMID 32483425, 2020). "Although the effect of EZ on the activity of serum aminotransferase and serum TNF-α was lower than that of JG, EZ more effectively reduced mortality and inhibited apoptosis in GalN/LPS-injected mice, verifying the important role of apoptosis in Liuweiwuling action on liver failure." (PMID 29618826, 2018). "Furthermore, the TNF-α-induced liver failure and exacerbation of liver damage following exposure to the hepatotoxin CCl4 were abrogated by treatment with a soluble TNF receptor and were inhibited in TNF-knockout mice." (PMID 27046197, 2016). "This triggers a robust inflammatory cascade with the release of pro-inflammatory cytokines such as tumor necrosis factor (TNF-α) and interleukin-6 (IL-6), driving hepatocellular damage and liver failure." (PMID 41163775, 2025). "Liver failure was induced by hepatotoxic drugs, such as APAP, LPS, D-GalN, CCL4, human serum albumin (HSA), concanavalin-A, and TNF, or surgical simulation including cecal ligation puncture, partial hepatectomy, and bile duct ligation." (PMID 38172209, 2024). "Most researchers used paracetamol (APAP), LPS, D-GalN, CCL4, TNF-α, TGF-β1, and multiplicity of infection(MOI) to induce the liver failure model." (PMID 38172209, 2024).